SIRT1 (sirtuin 1)
Diseases named in the same sentence as SIRT1 in open-access papers (continued):
Sharing a sentence is not in itself a finding about the gene and the disease.
lung carcinoma (continued). "Briefly, different versions of HA-tagged N1IC (HA-N1IC) were expressed in lung cancer-derived ECs with vectors encoding either SIRT1 or a SIRT1 mutant lacking deacetylase activity (SIRT1 H363Y)." (PMID 23028940, 2012). "In lung cancer these include the lysine acetyltransferases KAT13D (Clock), KAT5 (Tip60), KAT2B (PCAF) and KAT13B (SRC-3), while SIRT-1 expression has been linked to cisplatin resistance in epidermoid and hepatoma cells." (PMID 24212667, 2011). "Accordingly, SIRT1 ISGylation promoted lung cancer progression and limited lung cancer cell sensitivity to DNA damage-based therapeutics in in vivo and in vitro models, and elevated expression of SIRT1 and ISG15 was associated with poor prognosis in lung cancer patients." (PMID 38443596, 2024). "Additionally, high levels of SIRT1 and ISG15 in lung cancer tissues were linked to worse outcomes." (PMID 38443596, 2024). "Therefore, we investigated whether the KRASMut-ERK/MAPK-c-Myc axis increases SIRT1 or SIRT2 expression in KRASMut lung cancer cells." (PMID 37779142, 2023). "We hypothesized that SIRT1 is a valuable target for KRASMut lung cancer." (PMID 37779142, 2023). "Therefore, to examine whether SIRT1 K/D affects KRASMut-driven proliferation in lung cancer cell lines, we performed cell viability assays and colony formation assays in H358, A427, and H727 cells after SIRT1 K/D." (PMID 37779142, 2023). "Likewise, E2F1 was also found to be negatively regulated by SIRT1 in the lung cancer cell line." (PMID 32165863, 2020). "Therefore, targeting SIRT1 might be a new strategy to manage the chemoresistance of lung cancer, and probably other cancers." (PMID 31043584, 2019). "Therefore, targeting SIRT1 might be a new therapy option for chemoresistant lung cancer, and probably other cancers." (PMID 31043584, 2019). "However, the function and relevance of SIRT1 to chemoresistance of lung cancer cells was largely unknown." (PMID 31043584, 2019). "Sirtuin 1 (SIRT1) is known to play a role in a variety of tumorigenesis processes by deacetylating histone and non‐histone proteins; however, antitumour effects by suppressing SIRT1 activity in non‐small cell lung cancer (NSCLC) remain unclear." (PMID 30710424, 2019). "Consequently, the expression of SIRT1 protein was significantly inhibited by the overexpression of miR-30a in A549 and H1975 cells, while the miR-30a inhibitor significantly increased the SIRT1 protein levels in lung cancer cells." (PMID 29435152, 2018). "Therefore, SIRT1 inhibition might be an effective therapeutic strategy for the treatment of lung cancer." (PMID 29312612, 2017). "In this study, we showed that the NSAIDs celecoxib and sulindac suppress lung cancer migration and invasion by inhibiting TGF-β1-induced EMT, and that NSAID-induced EMT inhibition in lung cancer may be attributed, at least partially, to a SIRT1-mediated pathway." (PMID 27528025, 2016). "Therefore, SIRT1 expression was significantly up-regulated in lung cancer." (PMID 26318035, 2015). "Thus SIRT1 was responsible for B[a]P-induced sustained inflammation and lung cancer development." (PMID 26318035, 2015). "Thus, targeting SIRT1 activity or/and gene expression may represent a novel mechanism in the treatment of lung cancer." (PMID 23028940, 2012). "This prompted us to investigate the mechanism by which SIRT1 activity was increased and the role of pSIRT1 in the chemoresistance of KRASMut lung cancer cells." (PMID 40935852, 2025). "Various molecular pathways and genes such as BMAL1, SIRT1, HLF, and PER1 and their implications in aging, circadian rhythms, and lung cancer will also be discussed." (PMID 39812541, 2025). "Compared with SIRT1 depletion, SIRT1 WT and SIRT1 KR complementation significantly increased tumor growth in BALB/c nude mice, substantiating the importance of SIRT1 in driving lung cancer progression." (PMID 38443596, 2024).
lung carcinoma (continued). "In a separate study, SIRT1 inhibited proteasomal degradation of XRCC1, leading to cisplatin resistance in lung cancer cell lines." (PMID 38659583, 2024). "SIRT1 upregulation has already been demonstrated in some cancer cells, such as esophageal squamous cell carcinoma (ESCC), lung cancer, and colon cancer." (PMID 38828455, 2024). "From the perspective of clinical relevance, we revealed that SIRT1 and ISG15 were upregulated in primary lung adenocarcinoma tissues from lung cancer patients compared to the corresponding adjacent normal tissues." (PMID 38443596, 2024). "To further extend our observations to a clinicopathologically relevant context, we analyzed the protein expression levels of SIRT1 and ISG15 in NSCLC patients-derived lung cancer tissues." (PMID 38443596, 2024). "Through the SIRT1/AMPK signaling pathway, it activates the formation of autophagosomes and increases the number of autophagolysosomes in lung cancer A549 cells, thereby promoting cell apoptosis." (PMID 38245694, 2024). "We found that the expression of up‐regulated hub DEAMGs BCL2L1, CASP8, SIRT1 and CCL2 in lung cancer tissues with high metastasis was dramatically increased compared with lung cancer tissues with low metastasis." (PMID 37850256, 2024). "The research, conducted on human cells, mice, and human lung cancer tissues, revealed that when ISG15 conjugates to SIRT1, it boosts SIRT1’s activity, encouraging tumor growth and reducing the effectiveness of a chemotherapy drug." (PMID 38443596, 2024). "SIRT1 upregulation has already been demonstrated in various cancer cells, such as esophageal squamous cell carcinoma (ESCC), lung cancer, and colon cancer." (PMID 38828455, 2024). "However, compared to SIRT1 KR complementation, SIRT1 WT complementation in SIRT1 KO cells markedly attenuated the doxorubicin-mediated inhibition of clonogenic growth, suggesting that SIRT1 ISGylation is required for lung cancer cell proliferation and survival." (PMID 38443596, 2024). "UBC9/PIASy-mediated SUMOylation decreases sirtuin 1 (SIRT1) and increases transcriptional repression activity of SLUG, predicting more invasive types of lung cancers." (PMID 37415251, 2023). "Clinical lung cancer samples revealed a positive correlation between PGC-1α (PPARGC1A) and SIRT1 expression." (PMID 35681729, 2022). "SIRT1, HIF1α and VEGFA protein expression in DDP-induced chemotherapy-resistant lung cancer tissues were declined when miR-326 was overexpressed." (PMID 34696659, 2022). "SIRT1 was found to be overexpressed in the gefitinib (an EGFR-TKI) resistant PC9 and HCC827 lung cancer cells lines, which were also significantly enriched in CSCs compared to the parental cells." (PMID 36497394, 2022). "We showed that Sal inhibited TGF- β1-induced EMT and suppressed lung cancer migration and invasion, which involved the AMPK/SIRT1-mediated signaling pathway." (PMID 33437206, 2021). "The results indicated that, in addition to pancreatic cancer, SIRT1 and CUL4B are also significantly upregulated in esophagus, stomach, rectum, liver, and lung carcinomas, compared with adjacent normal tissues." (PMID 34163012, 2021). "Taken together, results from these inhibitor studies suggest SIRT-1 and SIRT-3 play important roles in mediating TL-induced down-regulation of CAV-1 protein expression in A549 and NCI-H460 lung cancer cells." (PMID 32733649, 2020). "Inhibition of SIRT1 impaired HR repair activity, which sensitized the lung cancer cells to WEE1 inhibitor MK-1775-induced DNA damage and apoptosis in lung cancer xenograft model." (PMID 33194676, 2020). "To further investigate the mechanism of PPD in lung cancer, we evaluated the inhibitory effect of PPD on SIRT1 in vitro." (PMID 31133857, 2019). "In lung cancer and ovarian cancer, SUMO E3 ligase PIASy suppresses SIRT1 expression by reducing SP1 occupancy of the promoter of SIRT1 and thus promotes metastasis." (PMID 30250020, 2018).
lung carcinoma (continued). "Moreover, SIRT1 could contribute to the development of lung cancer through TNF-α/β-catenin axis." (PMID 28977967, 2017). "Our findings implicate overexpressed SIRT1 as a potential therapeutic target to reverse TGF-β1-induced EMT and to prevent lung cancer cell migration and invasion." (PMID 27528025, 2016). "We examined the involvement of SIRT1 in TGF-β1-induced EMT during the migration and invasion of lung cancer cells in this study." (PMID 27528025, 2016). "We confirmed that SIRT1 is induced during the early stages of tumor progression by TGF-β1 and is essential for the oncogenic functions of TGF-β1 in lung cancer." (PMID 27528025, 2016). "In this study, we showed that SIRT1 is a pivotal positive regulator of TGF-β-induced EMT and lung cancer migration, and invasion by NSAIDs." (PMID 27528025, 2016). "In order to investigate the functional role of SIRT1 and SIRT2 in NSCLC, we downregulated their expression in two lung cancer cell lines, A549 and H1299, using two different siRNAs for each gene." (PMID 25915617, 2015). "To study the significance of SIRT1 and SIRT2 overexpression in human lung cancer, we analyzed their protein levels in a cohort of 105 NSCLC patients by immunohistochemistry." (PMID 25915617, 2015). "To examine the effect of SIRT1 on lung cancer angiogenesis, we established LLC xenograft models with endothelial cell-specific SIRT1 and SIRT1 H363Y expression in transgenic mice." (PMID 23028940, 2012). "Treatment with the SIRT1 activity inhibitor triggered the anticancer effects of cisplatin and pemetrexed in human lung cancer cells, lung orthotopic tumors and a spontaneous in vivo model of KRASMut lung cancer." (PMID 40935852, 2025). "In addition, coimmunoprecipitation and western blotting analyses conducted in the NCI-A549 cell line validated the interaction of SIRT1 with β-catenin and YAP in lung cancer cells." (PMID 39266996, 2024). "The combination of cisplatin and erlotinib with the SIRT1 inhibitor EX527 shown synergistic anticancer effects; however, in lung cancer, EX527-mediated inhibition of SIRT1 increased the efficacy of erlotinib by decreasing cell proliferation, augmenting DNA damage, and increasing apoptosis." (PMID 39479446, 2024). "Interestingly, the levels of not only SIRT1 but also ISG15 and protein ISGylation conjugates were elevated in six of the lung cancer tissues (54.5%), suggesting the involvement of ISG15 and SIRT1 in lung cancer development." (PMID 38443596, 2024). "QR can activate the SIRT1/AMPK signalling pathway to induce apoptosis in A549 and H1299 lung cancer cells, but its anticancer mechanism on LUSC remains unclear." (PMID 36605099, 2022). "In lung carcinomas, UBC9 was identified as a metastasis-promoting oncogene through enhancing the transcriptional repression activity of the oncogene Slug or suppressing expression of the tumor suppressor gene Sirt1." (PMID 35460552, 2022). "Research on the invasion and migration of lung cancer cells found that resveratrol, a SIRT1 agonist, could curb the occurrence of EMT to downsize the invasion and migration of lung cancer cells." (PMID 35958178, 2022). "In conclusion, we demonstrated that Sal suppresses lung cancer cell migration and invasion by inhibiting TGF-β1-induced EMT, and that it may be partially attributed to the AMPK/SIRT1 pathway." (PMID 33437206, 2021). "In lung cancer cells, S-nitrosylation of the H2O2-eliminating enzyme Prdx2 (peroxiredoxin-2) led to increases in H2O2 levels, which activated AMPK, followed by phosphorylation of SIRT1 and, thus, abolishment of its deacetylating activity." (PMID 34279445, 2021).
lung carcinoma (continued). "Nonetheless, these inhibitor studies indicate that SIRT-1 and SIRT-3 play pivotal roles in mediating TL-induced down-regulation of CAV-1 protein expression in A549 and NCI-H460 lung cancer cells, further supporting the importance of SIRT-3 in TL-mediated cytotoxicity." (PMID 32733649, 2020). "Mechanistic studies revealed that miR-30a could directly target the SIRT1 3′-UTR and inhibit its expression in lung cancer cells." (PMID 29435152, 2018). "For exmple, SIRT1 was reported to be a tumor promoter in lung adenocarcinoma and can enhance β-catenin accumulation then to activate TNF-α transcription, leading to sustained inflammation and lung cancer development." (PMID 28977967, 2017). "Our results support the hypothesis that SIRT1 and SIRT2 have a protumorigenic role in lung cancer, promoting cell proliferation." (PMID 25915617, 2015). "In summary, our results support the hypothesis that SIRT1 and SIRT2 have a protumorigenic role in lung cancer, promoting cell proliferation." (PMID 25915617, 2015). "SIRT1 could stimulate tumor growth by increasing vessel density and downregulating DLL4/Notch signaling in lung cancer." (PMID 26318035, 2015). "In lung cancer, previously published results about the role of SIRT1 and or SIRT2 have not provided a clear and definite answer." (PMID 25915617, 2015). "Furthermore, transfection of lung cancer-derived ECs with N1IC, the acetyltransferase p300, and increasing amounts of SIRT1 revealed that p300 was capable of acetylating N1IC and enhancing N1IC transcriptional activity." (PMID 23028940, 2012). "In contrast to our hypothesis, SIRT1 K/D could not completely abolish the proliferation of KRASMut lung cancer cells." (PMID 37779142, 2023). "Therefore, we estimated the level of SIRT1 expression to analyze whether it could be modulated by RESV and/or PRI-2191 in lung cancer cells." (PMID 33652978, 2021). "In summary, our study demonstrates that GSNO could induce lung cancer cell apoptosis via nitrosylating Prdx2 to induce H2O2 accumulation, subsequently increasing AMPK phosphorylation and further inhibiting the activity of SIRT1." (PMID 30988280, 2019). "In addition, SIRT1 negatively regulated the activity of Notch1 signaling in endothelium of lung cancer and inhibited N1IC expression which leading to endothelial cell proliferation and promoting the growth of lung cancer." (PMID 25420528, 2014). "Furthermore, SIRT1 is a potential predictor of poor prognosis in NSCLC patients treated with platinum-based chemotherapy, and SIRT1 downregulation greatly increases chemosensitivity to cisplatin, indicating the important role of SIRT1 in driving lung cancer development and chemoresistance." (PMID 38443596, 2024). "It is not clear whether SIRT1 overexpression alone is sufficient to induce EMT in lung cancer." (PMID 27528025, 2016). "Therefore, the role of SIRT1 and SIRT2 in lung cancer remains unclear." (PMID 25915617, 2015). "Herein, we report that the nicotinamide adenine dinucleotide 1 (NAD1)-dependent deacetylase SIRT1 can function as an intrinsic negative modulator of Delta-like ligand 4 (DLL4)/Notch signaling in Lewis lung carcinoma (LLC) xenograft-derived vascular endothelial cells (lung cancer-derived ECs)." (PMID 23028940, 2012). "ActD increased expression and activity of SIRT1 in drug-resistant LS513 colon cancer, OVCAR8-DXR ovarian cancer, and A549-DXR lung cancer cells, but not in ActD-sensitive SW620 colon cancer cells." (PMID 32151067, 2020).
lung carcinoma (continued). "However, the SIRT1 inhibitor nicotinamide could not restore HIC1 expression in lung cancer cells." (PMID 25486244, 2014). "Similarly, the silencing of SIRT1 significantly enhanced HEY1 and HEY2 expression in lung cancer-derived ECs in response to DLL4 stimulation, whereas no changes were observed in unstimulated lung cancer-derived ECs." (PMID 23028940, 2012).